CXCL12 (C-X-C motif chemokine ligand 12)
Diseases named in the same sentence as CXCL12 in open-access papers (continued):
Sharing a sentence is not in itself a finding about the gene and the disease.
rheumatoid arthritis (continued). "To improve our understanding of the relevance of this process to rheumatoid arthritis (RA), we have studied the mechanisms of presentation of exogenous CXCL12 by cultured RA ECs." (PMID 16507142, 2006). "During pathological conditions such as rheumatoid arthritis, HMGB1 is kept in its reduced isoform and can complex with CXCL12 enhancing cell migration and exacerbating the immune responses." (PMID 41937914, 2025). "In rheumatoid arthritis (RA), fibroblasts activated by tumor necrosis factor (TNF) produce high levels of chemokines such as IL-6, CXCL12, and CCL2, which enhance the recruitment and attraction of monocytes." (PMID 39290699, 2024). "In addition, HMGB1 in its reduced form binds to CXCL12 via the chemokine receptor CXCR4 in rheumatoid arthritis (RA), and a high concentration of CXCL12/HMGB1 hybrid complex is dependent on the JAK/STAT pathway to maintain the inflammatory response." (PMID 38156383, 2023). "Mechanistically, these expanded inflammatory Thy1+ fibroblasts were shown to drive inflammation in rheumatoid arthritis by secreting IL6 and chemokines such as CCL2, CX3CL1, CXCL9, and CXCL12." (PMID 35085231, 2022). "Currently, active study of the targeting of the CXCL12/CXCR4/CXCR7 axis in the treatment of malignancy, rheumatoid arthritis, and multiple sclerosis is being carried out." (PMID 36077592, 2022). "In rheumatoid arthritis, CXCR7 is expressed on endothelial cells in the synovium as well as on unstimulated human umbilical vein endothelial cells (HUVECs), and CXCR7 and CXCL12 are involved in angiogenesis." (PMID 32098047, 2020). "Based on the reports describing CXCL12-promoted recruitment of immune cells to inflamed tissues in autoimmune diseases such as rheumatoid arthritis (RA) and lupus erythematosus in lung inflammation and inflammatory bowel disease, CXCL12 has been proposed to have a pro-inflammatory role." (PMID 26300887, 2015). "Finally, comparative analysis with rheumatoid arthritis reveals JIA-enriched cell states, including NOTCH3+ and CXCL12+ sublining fibroblasts, suggesting potentially differential inflammatory programs in pediatric versus adult arthritis." (PMID 40894156, 2025). "TNFα, IL-1β, and hypoxia also up-regulate the expression of cytokines, including IL-6, CXCL8 (namely, IL-8), CCL2, CXCL11, CXCL12, and VEGF, as well as the expression of cytokine receptors such as TNFRSF9 in synovial fibroblasts derived from rheumatoid arthritis (RA) patients." (PMID 35967331, 2022). "Also, in rheumatoid arthritis, CXCR4 and CXCL12 have been proposed to be important in the disease precipitation." (PMID 27519689, 2016). "Similarly, in KEGG of “ Rheumatoid Arthritis”, we found that although Itgb2 and Cxcl12 do not act directly, they can cooperate in the activation of immune cells and VEGF signaling pathway to promote the inflammatory cells migration and angiogenesis." (PMID 37063847, 2023). "CXCL12, C3, FN1, COL1A2, ACTB, VCAM1, and MMP2 were identified and finally verified as the hub genes, mainly enriched in pathways like leukocyte transendothelial migration, PI3K-Akt signaling pathway, viral myocarditis, rheumatoid arthritis, and platelet activation." (PMID 36398072, 2022). "DC32, a dihydroartemisinin derivative, was found to significantly inhibit the transcription of chemokines (CXCL12 and CX3CL1) and IL-6 in rheumatoid arthritis (RA)." (PMID 34956376, 2021). "The chemokine CXCL12, also known as stromal cell-derived factor-1(SDF-1), has been identified as playing a crucial role in cell migration, angiogenesis, tumor cells proliferation and metastasis, as well as in autoimmune diseases such as rheumatoid arthritis (RA)." (PMID 33129326, 2020). "Moreover, studies in patients with rheumatoid arthritis (RA) showed that fibroblast-like synoviocytes (FLS) constitutively express CCR2, CCR5, CXCR3,and CXCR4; in addition, stimulation with CCL2, CXCL12, CXCL9, and CXCL10 enhances FLS migration and proliferation." (PMID 28883822, 2017).
rheumatoid arthritis (continued). "The CXCL12/CXCR4 axis also participates in the recruitment of inflammatory cells as shown in animal models of allergic airway disease and rheumatoid arthritis (RA)." (PMID 16507142, 2006).
breast tumor (60 papers, 2005 to 2025). "Consequently, our work supported that the joint stratification of TMB and CXCL12-related risk score could be used to categorize breast tumors into distinct outcomes." (PMID 37564657, 2023). "CXCR4 was found on the surface of murine breast tumour 4T1 BC cells, and it was found to increase breast tumour development and metastasis when combined with the chemokine CXCL12 (SDF-1)." (PMID 37162544, 2023). "The CXCL12 expression level was higher in neoplastic lung tissue, which was occupied with breast tumours." (PMID 37162544, 2023). "Histology analysis of the resected breast tumors before treatment and the small nodules detected after treatment and detected reduced protein levels of S100a9 and Cxcl12." (PMID 35304461, 2022). "CXCL12 secreted by osteoblasts was shown to induce the survival of disseminated breast tumor cells expressing the CXCR4 receptor by upregulating the Akt pathway via c-Src activation." (PMID 33987095, 2021). "Roles for CXCR4 in resistance to endocrine treatments were also demonstrated when CXCL12 administration has increased the volumes of tumors generated by luminal-A breast tumor cells in mice treated by the estrogen receptor antagonist Fulvestrant." (PMID 32582148, 2020). "Elevated production of functional MMP2 and MMP9 was detected in breast tumor cells following CXCL12 stimulation, in the context of CXCR4 expression." (PMID 32582148, 2020). "Co-implantation of human CAFs secreting CXCL12 with tumor cells enhances breast tumor growth with CXCL12 recruiting endothelial cells to enhance angiogenesis." (PMID 33414786, 2020). "Mechanistic analyses indicated that over-expression of CXCL12 in breast tumor cells has led to E-cadherin reduction through activation of the NF-κB pathway and by up-regulation of β-catenin expression." (PMID 32582148, 2020). "Several preclinical studies targeting the CXCR4/CXCL12 axis have been recently conducted in breast tumors." (PMID 30012106, 2018). "Our data suggest a mechanism whereby CAFs promote tumor cell migration and invasion through CXCL12 secretion to regulate the mDia2-directed cytoskeleton in breast tumor cells." (PMID 29596520, 2018). "Based in many in vitro and in vivo evidences, nowadays, it is widely accepted that CXCR4/CXCL12 axis is involved in tumor growth, migration and invasion of human breast tumor cells." (PMID 30012106, 2018). "Previous studies have analyzed that higher expression level of CXCL12 lead the breast tumor towards metastasis." (PMID 28929029, 2017). "In vitro experiments revealed that MB231/miANGPTL2 attenuates breast tumor cell responsiveness to CXCL12 stimulation by decreasing CXCR4 expression in those cells." (PMID 25773070, 2015). "This suggests that metastatic breast tumor cells selectively express CXCR4 which leads them to organs with high expression levels of CXCL12." (PMID 24259307, 2013). "In this paper, we describe how the expression of CXCL12 by breast tumor cells can enhance in vivo invasion in the tumor microenvironment through recruitment of macrophages." (PMID 22314082, 2012). "This study provides novel insights into the crosstalk between CB2 and CXCR4/CXCL12-signaling pathways in the modulation of breast tumor growth and metastasis." (PMID 21915267, 2011). "In this study, we evaluated the methylation patterns of ESR1 and two CpG islands in the CXCL12 gene in breast tumour samples from Brazilian women." (PMID 20109227, 2010). "CXCL12 promoter hypermethylation has been detected in primary breast tumours and contributes to their metastatic potential." (PMID 20109227, 2010). "We also used 5-aza-2'-deoxycytidine (5-aza-CdR) treatment and DNA bisulphite sequencing to study the promoter methylation for a specific region of CXCL12 in breast tumour cell lines." (PMID 20109227, 2010). "We also confirmed that more CXCL12 was expressed in serum of breast tumour-bearing mice." (PMID 37162544, 2023).
breast tumor (continued). "Moreover, CXCL12 production was elevated when CAFs or MSCs interacted directly or indirectly with breast tumor cells." (PMID 32582148, 2020). "Finally, the tumor vasculature has also been targeted by OVV-CXCR4-A-mFc, a VV expressing a CXCR4 antagonist, which is directed against the VEGF-induced pro-angiogenic CXCL12/CXCR4 signaling pathway in human breast tumor cells." (PMID 33167307, 2020). "This potential mechanism for the formation of gradients directed into the vasculature is supported by a statistical bioinformatics study of The Cancer Genome Atlas, which concluded that low CXCL12 levels in breast tumors correlated with more aggressive disease." (PMID 29117251, 2017). "When compared against stromal cells derived from primary breast tumors or healthy breast tissue, they found that the stromal cells that had lodged themselves in the brain expressed the highest levels of CXCL12 and CXCL16, two chemokines involved in cell movement." (PMID 28649646, 2017). "Furthermore, COUP-TFI and the CXCL12 signaling axis are dysregulated in breast tumor biopsies compared to normal epithelium." (PMID 28666461, 2017). "Indeed, breast tumor aggressiveness has been associated with increased COUP-TFI expression, decreased CXCL12 and CXCR7 expression, and increased CXCR4 expression." (PMID 28666461, 2017). "Importantly, our results indicate that NCoR and TRβ not only silence the expression of CXCR4 receptors in the breast tumor cells, but also reduce the production of its ligand, CXCL12, by the tumor environment." (PMID 27806339, 2016). "We conclude that tumor cell-derived ANGPTL2 may increase bone metastasis by enhancing breast tumor cell responsiveness to CXCL12 signaling through up-regulation of tumor cell CXCR4 expression." (PMID 25773070, 2015). "The CXCL12 MSP results from breast tumour cell lines were identical for the two islands." (PMID 20109227, 2010). "First, we analysed CXCL12 expression in breast tumour cell lines by RT-PCR." (PMID 20109227, 2010). "We first analysed the CXCL12 expression pattern in seven breast tumour cell lines using RT-PCR." (PMID 20109227, 2010). "In addition, bone-derived CXCL12 may have systemic effects, promoting the growth and dissemination of primary breast tumors and facilitating their metastasis to the bones." (PMID 35565202, 2022). "Therefore, disrupting the CXCL12/CXCR4 axis may impinge on the survival of dormant breast tumor cells or induce the outgrowth of prostate tumor cells." (PMID 33987095, 2021). "Among these, CXCL12 (SDF-1) is a key molecule, and CXCL16 can also chemotactically recruit monocytes to breast tumor tissues." (PMID 40890855, 2025). "We also found that there were increased Pdl1 and Pd1 staining in breast tumor tissues from Brca1Co/Co;MMTV-Cre treated either with Tas for S100A9 or AMD3465 which is an inhibitor for CXCR4, a receptor for CXCL12." (PMID 35304461, 2022). "Although C-X-C motif chemokine 12 (CXCL12) has been shown to bind to C-X-C chemokine receptor type 7 (CXCR7), the exact molecular mechanism regulations by CXCL12/CXCR7 axis in breast tumor growth and metastasis are not well understood." (PMID 24886617, 2014). "To confirm the epigenetic transcriptional silencing of CXCL12, we treated the MDA-MB-435, MDA-MB-436 and MDA-MB-231 breast tumour cell lines with the demethylating agent 5-aza-2'-deoxycytidine (5-aza-CdR)." (PMID 20109227, 2010). "In this study, we used methylation-specific PCR (MSP) to analyse the methylation status in two regions of the CXCL12 promoter and ESR1 in tumour cell lines and in primary breast tumour samples, and correlated our results with clinicopathological data." (PMID 20109227, 2010). "Thus, breast tumors generated by MMTV-neu:FAAH−/− mice expressed higher mRNA and protein levels of Cxcr4 and Cxcl12 than their FAAH-expressing counterparts, which is consistent with their enhanced aggressive behavior and metastatic rate." (PMID 37253733, 2023).
breast tumor (continued). "TGF-β not only induced tumour cell migration through the EMT process, but also increased the CXCR4 expressions in 4T1 tumour cells, which combined with CXCL12 to activate intracellular PI3K/Akt pathway, promoting the occurrence and metastasis of breast tumours." (PMID 37162544, 2023). "Upon intravenous administration, this virus blocked CXCL12/CXCR4 signaling, inhibiting the recruitment of circulating endothelial progenitors (CEPs) into the stroma and destructing the tumor vasculature in human breast tumor bearing mice." (PMID 33167307, 2020). "In particular, Cxcl12 expression was strongly enhanced in interleukin 7-producing fibroblasts and cell type-specific genetic ablation and systemic pharmacological inhibition revealed that the CXCL12/CXCR4 axis impacts breast tumor cell stemness." (PMID 29632733, 2018). "The involvement of the human CXCL12 ligand is questioned owing to very low expression levels, in line with the evidence that CXCL12 expression is higher in non-metastatic breast tumors, compared to metastatic ones." (PMID 26744352, 2016). "In this study, we report that a synthetic non-psychoactive cannabinoid that specifically binds to cannabinoid receptor CB2 may modulate breast tumor growth and metastasis by inhibiting signaling of the chemokine receptor CXCR4 and its ligand CXCL12." (PMID 21915267, 2011). "The MDA-MB-436, MDA-MB-435 and MDA-MB-231 breast tumour cell lines showed methylation of the two islands, which is in agreement with the observed lack of CXCL12 expression." (PMID 20109227, 2010). "In four of five samples, CXCL12 was found to be upregulated in the CAFs (data not shown), similar to reported findings in breast tumor stroma." (PMID 17922897, 2007). "However, another study demonstrated different roles for CXCR4 and CXCR7/ACKR3 in regulating estrogen-dependent growth of luminal breast tumor cells, where CXCR4 enhanced cancer cell growth and CXCR7/ACKR3 over-expression inhibited cell proliferation, possibly through CXCL12 sequestration." (PMID 32582148, 2020). "We used CXCL12 (also known as SDF-1α) and epidermal growth factor (EGF), two well-known extracellular signaling molecules that co-exist in the tumor microenvironment (e.g. lymph nodes or intravasation sites), and a malignant breast tumor cell line, MDA-MB-231, embedded in type I collagen." (PMID 23869217, 2013). "Since CXCL12 is expressed preferentially in lymph nodes, this may support our data that CXCR4 expression was significantly correlated with lymph node metastasis in human breast tumor samples." (PMID 19025611, 2008). "The expression profiles of CXCR4, CXCR7, CXCL12, and COUP-TFI mRNA in 82 breast tumors and control non-tumor samples were measured using real-time PCR." (PMID 24906407, 2014). "On the other hand, the breast tumour cell line MDA-MB-436 had a dense area of methylated DNA and did not regain expression of the CXCL12 gene when cultured with the demethylating agent 5-aza-CdR." (PMID 20109227, 2010).
osteosarcoma (59 papers, 2008 to 2025). A usually aggressive malignant bone-forming mesenchymal neoplasm, predominantly affecting adolescents and young adults. "In osteosarcoma (OG), CXCL12 was positively associated with inflammation, metastasis, cell cycle, differentiation, hypoxia, and negatively related to DNA repair, DNA damage, and invasion." (PMID 40166682, 2025). "The CXCL12 concentration was associated with an increase in the number of intra-tumor lymphocytes in the osteosarcoma samples, highlighting the potential role of CXCL12 in lymphocyte homing to the primary tumor." (PMID 34834449, 2021). "Researchers have reported that CXCL12 is associated with the survival outcome in the osteosarcoma." (PMID 37537613, 2023). "On one hand, bone marrow MSCs promote migration and invasion through direct secretion of several cytokines such as C-X-C motif chemokine ligand 12 (CXCL12) that binds to C-X-C motif chemokine receptor 4 (CXCR4) or CXCR7 on osteosarcoma associated with lower overall patient survival." (PMID 31370265, 2019). "In osteosarcoma cell lines, inhibition of the CXCL12/CXCR4 signaling axis reduced cell proliferation in vitro and attenuated metastatic progression in vivo." (PMID 39896512, 2025). "Untreated osteosarcomas showed a positive correlation between CXCL12 concentration and the number of intratumoral lymphocytes." (PMID 40442778, 2025). "Activation of the OOCsystem by CXCL12/CXCR4 signaling is associated with heightened OSaggressiveness and accelerated metastasis, as CXCL12/CXCR4 is essentialfor restoring proliferative signaling in osteosarcoma cells." (PMID 41139822, 2025). "In osteosarcoma, epigenetically downregulated CXCL12 via DNA methyltransferase 1 (DNMT1) impairs CD8 + killer T cell homing to the tumour sites, consequently, metastatic cells evade immune mediated cytotoxicity." (PMID 40442778, 2025). "In osteosarcoma, CAFs secrete CXCL12, which can bind to CXCR4 on the surface of T cells, hindering their infiltration into the tumor core area." (PMID 40959080, 2025). "Epigenetic and other therapies targeting CXCL12 have the potential for therapeutic intervention in osteosarcoma leading to more favourable outcomes." (PMID 40442778, 2025). "Collectively, these data suggest that MIF is expressed by osteosarcoma cells and that CXCL12 is expressed by peritumoral stromal and/or immune cells." (PMID 39896512, 2025). "The communications between MSCs and osteosarcoma cells have been reported in previous studies, and many factors, including CXCL12, IL-6, and VEGF, have been proven to be included." (PMID 39582869, 2024). "In osteosarcoma, CXCL12/CXCR4 signaling promotes cancer progression and metastasis, and CXCR4 expression is associated with poor prognosis in patients." (PMID 37025604, 2023). "Osteosarcoma patients with high levels CXCL12 in CAFs have better overall survival 148, and CXCL12 targeting can enhance the sensitivity of these tumors to immunotherapy." (PMID 36168619, 2022). "Fifteen cases of primary osteosarcoma were analyzed for established markers associated with CAR cells (LEPR, EBF3, CXCL12, PDGFRA) and subdivided into low‐grade parosteal (7/16) or high‐grade intramedullary (9/16) tumors." (PMID 35309866, 2022). "In osteosarcoma, the interaction between chemokine CXCL12 and its receptor CXCR4 drives the metastasis of osteosarcoma cells to the lung." (PMID 32974202, 2020). "The interaction of CXCR7/CXCL12 in the progression of osteosarcoma needs to be further investigated." (PMID 32974202, 2020). "Since healthy bones express CXCL12, osteosarcomas epigenetically decrease the expression of CXCL12 and impair T cell homing." (PMID 33096815, 2020). "Recently, the chemokine CXCL12/CXCR4 signaling has been extensively investigated in osteosarcoma due to the relevance in metastasis progression and poor patient outcome." (PMID 30093974, 2018). "Several targets of miR-23a were previously validated in other tumor cell types, including RUNX2 and CXCL12 in osteosarcoma." (PMID 27601936, 2016).